BAP1 (BRCA1 associated deubiquitinase 1)
Diseases named in the same sentence as BAP1 in open-access papers (continued):
Sharing a sentence is not in itself a finding about the gene and the disease.
tumor (continued). "BAP1 protein is a deubiquitinating enzyme, which serves as a tumour suppressor via regulation of DNA damage repair, cell cycle, and cellular differentiation." (PMID 28978163, 2017). "Positive nuclear immunoreactivity in tumour cells of surgical and cytology specimens was considered as retained BAP1 expression." (PMID 29085180, 2017). "Prior to the discovery of its key tumor suppressor role, BAP1 was primarily known for its role as a deubiquitinase." (PMID 29166932, 2017). "This suggests that the BAP1 tumor suppressor functions are tumor and context specific, which renders the elucidation of BAP1's role even more challenging." (PMID 29069806, 2017). "BAP1 overexpression group has a significant reduction in both tumor size and weight compared with the control plasmid group." (PMID 29159179, 2017). "Four SNVs of NOTCH2, PDE4DIP, ATP10B and NSD1 and one frameshift INDEL of BAP1 were validated by Sanger sequencing on tumour RNA." (PMID 28484631, 2017). "The 90 kDa protein was initially thought to reduce tumorigenesis through the deubiquitination of BRCA1, though it was later revealed that BAP1 can achieve its tumor suppressive role independently of BRCA1." (PMID 29166932, 2017). "Exogenous modulation of NEAT-1 and/or BAP1 expression altered tumor cell phenotype and modulated sensitivity to gemcitabine." (PMID 28122578, 2017). "The cell proliferation rate measured by the percentage of Ki-67-positive tumor cells was decreased in the group implanted with the BAP1 plasmid and increased in the group implanted with the miR-31 lentivirus." (PMID 26885612, 2016). "Conversely, silencing BAP1 expression reduced the early stage apoptotic cell population to 2.71 %, significantly lower than that of the control (5.25 %, p < 0.05), suggesting that BAP1 promotes tumor cell death by apoptosis and necrosis." (PMID 27553041, 2016). "Ino80 is downregulated in BAP1-defective cancer cells due to destabilization, suggesting a molecular basis for the BAP1 tumor-suppressor function." (PMID 27750218, 2016). "Expression of BAP1 was closely related to tumor status (p = 0.044), pTNM stage (p = 0.007), node status (p = 0.010), pleural invasion (p = 0.004) and post-operation relapse or metastasis (p = 0.0028)." (PMID 27553041, 2016). "A recent study demonstrates that Ino80 interacts with BRCA1-associated protein-1 (BAP1), a tumor suppressor that also stabilizes Ino80, in normal DNA replication." (PMID 27750218, 2016). "BAP1 is a tumor suppressor that is believed to modulate chromatin, regulate transcription, and possibly affect the ubiquitin-proteasome system and the DNA damage response pathway." (PMID 27057633, 2016). "The deubiquitinating enzyme BAP1 is an important tumor suppressor that has drawn attention in the clinic since its loss leads to a variety of cancers." (PMID 26739236, 2016). "BAP1 is important for tumor progression; however some BAP1-positive patients still develop metastases, suggesting that other pathways are important to drive metastatic outgrowth." (PMID 27507190, 2016). "For example, histone H2A regulates the expression of certain genes; deubiquitination of the BAP1 region is a critical step in tumor-suppressing function." (PMID 27800275, 2016). "Such fold change is biologically and physiological relevant, because the altered miR-31 also inhibited BAP1 expression and promoted the development of tumor, to the same degree as those obtained by using miR-31 mimics." (PMID 26885612, 2016). "Recent comprehensive genomic analyses of ccRCC revealed in addition to VHL mutations, recurrent mutations in several other ccRCC tumor suppressor genes including PBRM1, SETD2, and BAP1." (PMID 25826081, 2015). "Both early passage cell cultures and mouse xenograft tumors harbored the BAP1 mutations and CDKN2A deletions identical to those observed in the corresponding primary tumor." (PMID 25952750, 2015). "BAP1 is an established tumor suppressor, with its genomic locus being frequently deleted in human cancer." (PMID 26442100, 2015).
tumor (continued). "Transient overexpression of KLF5 partially but significantly rescued the BAP1 knockdown-induced tumour growth suppression." (PMID 26419610, 2015). "I will next focus on USP44 and BAP1, which have been best characterized as tumor suppressors in human pathology." (PMID 26442100, 2015). "Significant, tumour-specific loss of heterozygosity occurs in nine genes (ATM, BAP1, BRCA1/2, BRIP1, FANCM, PALB2 and RAD51C/D)." (PMID 26689913, 2015). "Loss of heterozygosity (LOH), a common somatic rearrangement of the BAP1 gene commonly found in MM and other tumors, was confirmed by tumor tissue DNA sequencing in MARF11-III-1 and MARF18-III-1, for which tumor tissue was available." (PMID 26683624, 2015). "These prefibrillar aggregates of BAP1 induce cytoxicity in HEK 293T cells which is contrary to its tumor suppressor function." (PMID 26680512, 2015). "In conclusion, BAP1 is a KLF5 DUB and BAP1 promotes basal breast cell proliferation, migration, tumour growth and metastasis partially through stabilizing KLF5." (PMID 26419610, 2015). "Based on our cohort (n = 14), we estimate that among patients harboring a mutation in PBRM1, SETD2, BAP1, or KDM5C, the mutation would be present in 75%, 70%, 58%, and 55% of the tumor, respectively." (PMID 25124064, 2014). "NGS performed on a tumor sample from a liver biopsy obtained at the time of diagnosis revealed NF1 mutation R1241*, BAP1 truncation (exon 12), and CTNNB1 mutation N387K." (PMID 24931142, 2014). "For example, all the SETD2 and BAP1 somatic mutations and the majority of PBRM1 mutations were found in the branches of the tumor phylogenetic trees." (PMID 25159823, 2014). "BAP1 (BRCA1-Associated Protein 1) was initially identified as a protein that binds to BRCA1 and is now recognized as a tumor suppressor that mediates its effects through chromatin modulation, ubiquitin-proteasome system and the DNA damage response pathway." (PMID 25536104, 2014). "We and others have reported the associations of PBRM1, SETD2, BAP1, and KDM5C mutations with advanced stage, grade, and tumor invasiveness, and discovered that SETD2 and BAP1 mutations are associated with lower cancer-specific survival rates." (PMID 25124064, 2014). "Based on the mutations' prevalence we estimated that three different tumor regions should be sampled to detect mutations in PBRM1, SETD2, BAP1, and/or KDM5C with 90% certainty." (PMID 25124064, 2014). "In our cohort, we estimated that a minimum of three tumor regions must be sampled to detect mutations in PBRM1, SETD2, BAP1, and/or KDM5C with 90% certainty." (PMID 25124064, 2014). "The role of BAP1 as a tumor suppressor gene was further supported by LOH of the wild type allele in UMM tumor tissue of II:11." (PMID 23977234, 2013). "Functionally, BAP1 is a nuclear deubiquitinating enzyme that has tumor suppressive activities in conjunction with and also independent of BRCA1." (PMID 22545102, 2012). "BAP1 is a tumor suppressor gene located on chromosome 3p21 and the BAP1 protein is involved in DNA damage response, regulation of cell cycle and cell growth." (PMID 22613358, 2012). "The significance of this result is unclear but BAP1 has been described as a candidate tumour suppressor gene." (PMID 18691394, 2008). "Patients with available tumor tissue 83.3% (5/6) showed evidence of BAP1 biallelic inactivation." (PMID 41670784, 2026). "In this minireview, we aim to shed light on the roles of PBRM1, SETD2, and BAP1 in the tumor metabolic and immune microenvironments, and discuss how these functions could benefit the management of advanced ccRCC." (PMID 41602827, 2026). "ML-based frameworks for WSI IHC analysis are being developed for the automated detection of BRCA1-Associated Protein 1 (BAP1) loss, which has retrospectively been associated with higher tumour grade, increased metastatic potential, and poorer clinical outcomes in clear cell RCCs." (PMID 41590351, 2026).
tumor (continued). "Such tumor profiling could offer key insights—identifying particular somatic mutations (e.g., in VHL, FH, or BAP1) may prompt testing for the same mutation in germline DNA." (PMID 41562811, 2025). "BAP1 deficiency leads to mitochondrial morphological abnormalities and 4‐HNE protein downregulation, while exogenous BAP1 restoration inhibits tumor progression through liproxstatin‐1‐sensitive ferroptosis mechanisms, confirming the critical in vivo role of this pathway." (PMID 40919133, 2025). "None of the remaining patients with BAP1 germline mutations developed a malignant tumour diagnosis during the follow‐up period (follow‐up period range = 8–111 months, mean = 49 months)." (PMID 39268598, 2025). "Extensive genomic analyses have revealed frequent inactivation of key tumor suppressors, such as neurofibromin 2 (NF2), BRCA1-associated protein 1 (BAP1), and cyclin-dependent kinase inhibitor 2A (CDKN2A), through various mechanisms, thereby providing new targets for treatment." (PMID 40362535, 2025). "The JX-594-induced decrease in tumor volume was the most significant in tumors associated with BAP1 mutations as opposed to tumors with VHL, PBRM1, and SETD2 mutations (P < 0.01)." (PMID 40856833, 2025). "Loss of BAP1 leads to a dramatic reduction of MHC-II gene expression and reduced immune cell infiltration in animal models, resulting in a substantial acceleration of tumor growth." (PMID 39817454, 2025). "We found that BAP1 staining in cells corresponded to tumor tissues." (PMID 39920655, 2025). "In addition, our work has elucidated the context-dependent oncogenic/tumor-suppressive function of BAP1 and highlighted the potential of therapeutically attenuating PRC1 activity in BAP1-deficient cold tumors." (PMID 39817454, 2025). "BAP1, as a tumor suppressor, is involved in chromatin remodeling and gene expression regulation." (PMID 39858033, 2025). "The proliferation of BAP1-deficient cells depends on the status of BECN1 tyrosine phosphorylation, which may contribute to tumor progression in certain cancer types." (PMID 40754831, 2025). "Tumours with intact BAP1 staining were classified as Class A/B tumours." (PMID 40241171, 2025). "BAP1 exerts its tumor-suppressive effects by inhibiting the JNK/c-Jun pathway, suggesting that the JNK signaling pathway could serve as a potential therapeutic target in ICC." (PMID 40421086, 2025). "BAP1, a tumor suppressor, utilizes its deubiquitinating activity to modulate a number of processes, including DNA damage repair, cell cycle control, programmed cell death, cellular differentiation, cell proliferation, chromatin modification, and the immune response." (PMID 40688406, 2025). "Of note, knockdown of BAP1 promoted intrahepatic tumor metastasis, with both BAP1 knockdown groups (shBAP1#1 and shBAP1#3) showing more frequent irregular tumor borders with invasion into the adjacent liver parenchyma, more frequent tumor microsatellite formation and venous invasion." (PMID 39984455, 2025). "This interaction might disrupt BAP1’s ability to maintain genomic stability, facilitating tumor progression." (PMID 39858033, 2025). "NGS would be valuable to profile inactivating mutations in the BAP1 gene in these tumours, but was not available." (PMID 39976080, 2025). "Examining the role of BAP1 in the tumor microenvironment, as well as exploring the influence of BAP1 on inflammatory signaling pathways, could identify patients who are candidates for immunotherapy." (PMID 40361508, 2025). "Normal cells show nuclear BAP1 staining, while tumor cells with BAP1 loss show complete absence of staining." (PMID 40361508, 2025). "Our histopathological archives for BAP1‐inactivated tumours were searched from 2010 to 2022." (PMID 39268598, 2025). "Finally, we conducted immune cell profiling with our scRNA-Seq results and identified that the CD4+ effector memory–like (EM-like) T cell is the only immune cell population that is substantially reduced in BAP1-KO tumor tissues." (PMID 39817454, 2025).
tumor (continued). "The tumor had mutations in GNA11 (p.Q209P) and BAP1 (p.S583fs)." (PMID 40283643, 2025). "The tumor had mutations in GNA11 (p.Q209L) and BAP1 (c.68-13_82del28)." (PMID 40283643, 2025). "The tumor had mutations in GNAQ (p.Q209P) and BAP1 (p.P510fs)." (PMID 40283643, 2025). "Our data support this view regarding BAP1 as a tumor suppressor." (PMID 40136571, 2025). "BAP1 induces ferroptosis in tumor cells by downregulating SLC7A11 expression." (PMID 40822852, 2025). "BAP1 EZH2 overexpression suppresses tumor-suppressor genes and facilitates immune exclusion." (PMID 40661151, 2025). "Indeed, we previously showed that gene expression from tumor-infiltrating immune cells contributes substantially to the 15-GEP23 and that BAP1 loss in UM cells alters gene expression in adjacent immune cells." (PMID 41387680, 2025). "BAP1 loss in ccRCC defines an aggressive, HRD-like subset, in which early clinical data with the PARP inhibitor olaparib have shown signals of activity, including tumor shrinkage and durable disease control in patients with BAP1/DDR alterations." (PMID 41440218, 2025). "All these data support the notion that BAP1 functions as a tumor suppressor." (PMID 40136571, 2025). "This process underscores the molecular basis of BAP1’s tumor suppressor function." (PMID 39048965, 2024). "Notably, the 3p chromosome change impacts over 500 genes, featuring tumor suppressors like BAP1, FHIT, VHL, PTPγ, SEMA3B, SEMA3F, TUSC2, and MLH1." (PMID 39201328, 2024). "In BAP1-mutated UM, researchers found that ITGB2-ICAM1 signaling was enhanced between terminally exhausted CD8+ T cells and GDF15hiATF3hiCDKN1Ahi tumor cells, and inhibiting either ICAM1 or ITGB2 could prevent liver metastasis in the BAP1-mutated patients." (PMID 38966635, 2024). "However, mutations in BAP-1, often influenced by interactions with other genes like BRAF, can lead to a loss of its tumor-suppressive functions and contribute to the development of aggressive ccRCC." (PMID 39796121, 2024). "BAP1 is a deubiquitinating enzyme involved in several cellular processes, including transcriptional regulation, DNA repair, and metabolism, and it exhibits tumor suppressor activity in cancer cells." (PMID 39061150, 2024). "Chrysotile induced a more profound immune tumor response than crocidolite in Bap1-mutant mice by upregulating CD39/CD73-adenosine and Ccl2/Ccr2 pathways and recruiting more M2 macrophages, which together contributed to an immunosuppressive tumor microenvironment." (PMID 38592450, 2024). "UCHL3 and UCH37 are acknowledged oncogenes, while BAP1 is recognized as a tumor suppressor." (PMID 38965582, 2024). "Interestingly, we and others have recently found EZH2 to be overexpressed in tumors with loss of BAP1 function, thereby altering the chromatin distribution of PRC1 and PRC2 complexes and leading to a dependency on EZH2 for these tumor cells." (PMID 38054839, 2024). "Additionally, BRCA1-associated protein 1 (BAP1), a deubiquitinase for H2A, significantly inhibits tumor occurrence and development." (PMID 38965216, 2024). "In particular, BAP1 has been identified as a potential tumor suppressor in KIRC and type II KIRP." (PMID 39034372, 2024). "While clinical benefit was identified in the majority of patients with a mutated BAP1 tumor, the use of niraparib failed to meet the prespecified efficacy threshold of an objective response rate." (PMID 38054839, 2024).
tumor (continued). "However, a significantly increased tumor burdens in Bap1 knockout KPC mice was observed, and mice harboring Bap1 deletion exhibited poorer survival compared to those control KPC mice." (PMID 39350280, 2024). "When BAP1 loss occurs, this mutation is likely the driver in sporadic cases of clear cell RCC due to its association with low intratumoral heterogeneity and high tumor grade and proliferation." (PMID 38791999, 2024). "The BAP1 protein acts as a tumor suppressor and is often inactivated in ccRCC36,37." (PMID 38982123, 2024). "Except for four tumor specimens, the BAP1 status was correctly identified using IHC." (PMID 38349785, 2024). "Human tumor-associated mutations in BAP1 do not inhibit the expression of SLC7A11 and do not suppress tumors via promoting ferroptosis." (PMID 38267442, 2024). "Following previous work, BAP1 functioned as a significant tumor suppressor in human cancers." (PMID 38642144, 2024). "In addition, germline variations in BRCA1-associated protein 1 (BAP1) and other tumor suppressors have been related to the evolution of diffuse malignant PM in a subset of subjects." (PMID 40757547, 2024). "Finally, correct interpretation of the pathogenicity of variants is essential for refining the BAP1-TPDS phenotype, because its tumor profile depends on observation of true pathogenic variant carriers." (PMID 37956408, 2024). "BAP1+ patients had the larger range of tumor volumes, whereas BAP1− patients had the larger median." (PMID 39669009, 2024). "Importantly, data on tumor mass and mouse survival both indicate that Bap1 knockout tumors exhibited an unresponsive status to immune checkpoint blockade therapy, such as anti-PD1 antibody." (PMID 39350280, 2024). "Inactivation of BAP1 alters the metabolic status of different tissues and regulates various metabolic pathways such as lipids, nucleotides, and calcium ions, which have a broad role in tumor development." (PMID 39587076, 2024). "They showed that BAP1 loss was associated with favorable pathological tumor features, such as the papillary architecture and absence of tumor necrosis and concomitant CIS." (PMID 39272712, 2024). "In contrast we do not observe consistently lower (p-)ATM levels in the BAP1-deficient tumour cell lines." (PMID 38519707, 2024). "BAP1 was evaluated in 72% of tumor samples and was found to be deleted in 65%." (PMID 39624250, 2024). "We observed aberrant BAP1 protein levels with immunohistochemistry (IHC) in all seven tumours." (PMID 39766052, 2024). "Interestingly, the highest degree of tumor growth inhibition was observed in a PDX tumor model that contained biallelic mutations in two different HRR genes, namely, BAP1 and MRE11A (>100% TGI)." (PMID 38807759, 2024). "Furthermore, the interaction between UM tumor cells and CD8+ T-cells has been associated with poor prognostics and was stronger in BAP1-mutant cells using the activation of ITGB2 (integrin subunit beta 2) and ICAM1 (intercellular adhesion molecule 1)." (PMID 38920653, 2024). "However, chromosome 3 is home to multiple tumor suppressors important in many cancers (VHL, SETD2, PBRM1) in addition to BAP1, making it unclear in which cancers BAP1 loss is biologically important." (PMID 39554490, 2024). "Subsequently, it has been documented that BAP1 acts independently as a tumor suppressor, using its deubiquitinating activity to regulate proteins involved in cell proliferation, cell cycle control, cellular differentiation, DNA damage repair, chromatin modulation, cell death, and immune response." (PMID 38175637, 2024). "Overall, cooccurring deficiencies in BAP1, NF2, and CDKN2A/B might play an instructive role in tumor immunity and are closely related to patient prognosis." (PMID 38879686, 2024). "BAP1 is a tumor suppressor that regulates the BRCA1 growth control pathway." (PMID 39272712, 2024). "Tumor cells expressed a classical immunophenotype of mesothelial differentiation, with no BAP1 loss." (PMID 39059063, 2024).